CLPTM1L (CLPTM1 like)
Description:
Scramblase that mediates the translocation of glucosaminylphosphatidylinositol (alpha-D-GlcN-(1-6)-(1,2-diacyl-sn-glycero-3-phospho)-1D-myo-inositol, GlcN-PI) across the endoplasmic reticulum (ER) membrane, from the cytosolic leaflet to the luminal leaflet of the ER membrane, where it participates in the biosynthesis of glycosylphosphatidylinositol (GPI). GPI is a lipid glycoconjugate involved in post-translational modification of proteins. Can also translocate 1,2-diacyl-sn-glycero-3-phospho-(1D-myo-inositol) (phosphatidylinositol or PI), as well as several other phospholipids (1,2-diacyl-sn-glycero-3-phosphocholine, 1,2-diacyl-sn-glycero-3-phosphoethanolamine), and N-acetylglucosaminylphosphatidylinositol (GlcNAc-PI) in vitro.
Synonyms: CRR9; FLJ14400
Tractability: Antibody: UniProt predicts a signal peptide or a membrane-spanning region. PROTAC: ubiquitination databases record sites on it; its protein half-life has been measured.
Gene: Protein-coding gene on chromosome 5 (1,317,744 to 1,345,099, reverse strand). Ensembl gene ENSG00000049656.
Subcellular location: Endoplasmic reticulum membrane
Subcellular location (Human Protein Atlas): Endoplasmic reticulum
Gene Ontology:
Molecular function: phospholipid scramblase activity; protein binding
Biological process: plasma membrane phospholipid scrambling
Cellular component: endoplasmic reticulum; endoplasmic reticulum membrane; membrane; endomembrane system
Genetic constraint (gnomAD): Loss-of-function variants: 39 observed, 69.12 expected, observed/expected ratio (o/e) 0.56, 90% interval 0.44 to 0.74. The upper end of that interval is the gene's LOEUF score, 0.74, which puts it in group 3 of 6, group 1 being the genes least tolerant of losing a copy. Missense variants: 634 observed, 686.97 expected, observed/expected ratio (o/e) 0.92, 90% interval 0.86 to 0.99. Synonymous variants: 334 observed, 296.77 expected, observed/expected ratio (o/e) 1.13, 90% interval 1.03 to 1.23.
Homologues: Orthologues: macaque CLPTM1L (99% identical), dog CLPTM1L (95% identical), guinea pig CLPTM1L (95% identical), rat Clptm1l (95% identical), mouse Clptm1l (93% identical), pig CLPTM1L (93% identical), tropical clawed frog clptm1l (86% identical), zebrafish clptm1l (74% identical), rabbit CLPTM1L (60% identical), Drosophila melanogaster CG4332 (47% identical), Caenorhabditis elegans T13H5.8 (45% identical). Paralogues in human: CLPTM1 (36% identical).
Diseases named in the same sentence as CLPTM1L in open-access papers:
CLPTM1L is named in the same sentence as 76 diseases in open-access papers, as found by Europe PMC text mining. Sharing a sentence is not in itself a finding about the gene and the disease. The quoted sentences say what the papers report.
lung carcinoma (41 papers, 2010 to 2025). "GCG haplotypic structure of rs380286‐rs401681‐rs31487 variants on CLPTM1L gene is associated with skin and lung cancers in European population." (PMID 39031745, 2024). "In conclusion, the meta-analysis in this study demonstrated that CLPTM1L gene rs402710 and rs401681 polymorphisms were associated with a decreased risk of various types of cancer, especially for lung cancer among Asians." (PMID 29254260, 2017). "CLPTM1L gene rs402710 and rs401681 polymorphisms thus have a protective association with various types of cancer, especially lung cancer among Asians." (PMID 29254260, 2017). "In particular, we confirmed the association of rs401681 in an intronic region of CLPTM1L gene on chromosome 5, within the 5p15 susceptibility locus; the minor allele of rs401681 associated with a lower lung cancer risk (odds ratio, OR < 1)." (PMID 28181565, 2017). "The neighboring gene encodes cleft lip and palate associated transmembrane 1 like (CLPTM1L) protein that promotes growth and survival in pancreatic and lung cancer, respectively, and is overexpressed in some cancers." (PMID 27579533, 2016). "This suggested an inhibitory role in genotoxic stress-induced apoptosis, and identified CLPTM1L as an important factor affecting the survival of DNA damaged tumor cells and potentially lung cancer susceptibility." (PMID 25007268, 2014). "We identified that the minor alleles of rs451360, rs402710, and rs31484 in CLPTM1L were associated with a 0.52-fold, 0.76-fold, and 0.70-fold decreased risk of lung cancer in allelic model analysis, respectively." (PMID 25526467, 2014). "Genetic variants of cleft lip and palate trans-membrane 1-like (CLPTM1L) genes in the p15.33 region of chromosome 5 were previously identified to influence susceptibility to lung cancer." (PMID 25526467, 2014). "Like the TERT gene, CLPTM1L is also located at 5p15.33, which is a susceptible region for various cancers, including lung cancer." (PMID 25233467, 2014). "We examined the association of single nucleotide polymorphisms (SNPs) in CLPTM1L genes with lung cancer and explored their potential effects on the relationship between environmental risk factors (smoking, drinking) and lung cancer in a Chinese Han population." (PMID 25526467, 2014). "Our results verified that genetic variants of CLPTM1L contribute to lung cancer susceptibility in the northwest Chinese Han population." (PMID 25526467, 2014). "In several GWA studies, SNPs in TERT and CLPTM1L are associated with overall lung cancer and lung ADC." (PMID 25233467, 2014). "We genotyped 9 single nucleotide polymorphisms (SNPs) of CLPTM1L in a case–control study with 228 lung cancer cases and 301 controls from northwest China." (PMID 25526467, 2014). "We demonstrated that certain CLPTM1L genetic polymorphisms, rs402710, rs451360, and rs31484, are associated with the decreased risk of lung cancer in the northwest Chinese Han population." (PMID 25526467, 2014). "The association between CLPTM1L intronic SNP rs451360 and lung cancer has been evaluated in Caucasian6,21 and Chinese populations, which all demonstrated a statistically significant protective effect of rs451360." (PMID 25526467, 2014). "A common sequence variant, rs401681, located in an intronic region of CLPTM1L, has been reported to be associated with lung cancer risk based on genome-wide association study." (PMID 24386361, 2013). "CLPTM1L gene, which has been implicated in susceptibility to lung cancer, had a GxA effect in both skin and fat." (PMID 23889843, 2013). "Further more, a positive relationship between rs401681 C allele and shorter relative telomere length suggested that CLPTM1L gene was a candidate in affecting lung cancer susceptibility." (PMID 23738012, 2013). "The rs401681 polymorphism, located in an intronic region of CLPTM1L, has been reported to be associated with lung cancer risk based on genome-wide association study." (PMID 24386361, 2013).
lung carcinoma (continued). "The powerful genetic association between CLPTM1L and lung cancer inspired us to address the expression and function of this gene in detail." (PMID 23300716, 2012). "Common overexpression of CLPTM1L in lung tumors and a functional role in genotoxic stress induced apoptosis identify CLPTM1L as an important factor influencing survival of DNA damaged tumor cells and potentially lung cancer susceptibility." (PMID 22675468, 2012). "In the hope of defining the pathogenesis of CLPTM1L in lung cancer, we focused on CLPTM1L expression, cellular localization and functional association with lung cancer." (PMID 23300716, 2012). "Continued efforts to further define the genetic variation driving lung cancer susceptibility in this genetic region are an important next step in evaluating the relationship of CLPTM1L and other genes in the region with lung tumor susceptibility." (PMID 22675468, 2012). "A recent study provides multiple lines of evidence that the lung cancer association of rs31489 in the CLPTM1L gene is an independent observation from the association of rs2376100 in the TERT gene." (PMID 22675468, 2012). "In summary, our results show that genetic variation in the CLPTM1L-TERT locus of chromosome 5p15.33 is directly associated with the risk of lung cancer, most notably adenocarcinoma." (PMID 20700438, 2010). "Moreover, the CLPTM1L genomic region has been associated with susceptibility to other cancers, including cervical cancer, melanoma, lung cancer, and pancreatic cancer, underscoring its broader role in cancer susceptibility." (PMID 40550808, 2025). "The expression of CLPTM1L was observed to be elevated in lung adenocarcinoma and pancreatic cancer tissues compared to adjacent normal tissues, and poor clinical outcomes were associated with high CLPTM1L expression in patients with pancreatic and lung cancer." (PMID 38254939, 2023). "Some GWAS data illustrate that the region of CLPTM1L gene is associated with lung cancer." (PMID 34938740, 2021). "Also, genetic variants in TERT and CLPTM1L on chromosome 5p15.33 have been shown to be associated with risk of lung cancer." (PMID 26187382, 2015). "In addition to the allelic model analysis, the association between CLPTM1L SNPs and lung cancer risks was assessed using genetic models." (PMID 25526467, 2014). "Besides the allelic model analysis, we also performed genotypic model analysis to investigate the role of CLPTM1L variants on lung cancer risk." (PMID 25526467, 2014). "Our findings suggest that the interaction of genetic variants of CLPTM1L and environmental factors, especially tobacco smoking and alcohol consumption, may play an important role in occurrence of lung cancer in this population." (PMID 25526467, 2014). "Interestingly, one of the disease-associated variants (rs402710) underlying a GxA cis-eQTL in the cleft lip and palate associated transmembrane protein 1 gene (CLPTM1L) has been previously associated to lung cancer susceptibility and is located in a LD region that includes TERT." (PMID 23889843, 2013). "Genetic analysis has revealed that CLPTM1L is closely associated with lung adenocarcinoma and the genetic variance may cause abnormal gene expression, which plays an important role in the pathogenesis of lung cancer." (PMID 23300716, 2012). "The current study indicates that CLPTM1L also plays an important functional role in relation to cancer, and that this gene may to be at least partially responsible for the association of variants in the 5p15.33 region with lung cancer." (PMID 22675468, 2012). "CLPTM1L is overexpressed in several cancers, including lung cancer, renal cell carcinoma, and laryngeal squamous cell carcinoma." (PMID 41226525, 2025). "In lung cancer, oncogene CLPTM1L (cleft lip and palate-associated transmembrane 1 like protein) plays a pro-tumorigenic role and is critical for RAS-driven lung cancers." (PMID 36704521, 2022).
lung carcinoma (continued). "Some studies have found that the expression of CLPTM1L is significantly increased in lung cancer tissues compared with normal tissues by immunohistochemistry, especially in lung adenocarcinoma." (PMID 34938740, 2021). "The cisplatin resistance-related protein CRR9p (CLPTM1L) gene is overexpressed in lung cancer and knockdown of this gene prevents 95-D lung cancer cells from migrating and invading." (PMID 30079703, 2019). "The results showed that four genes (GATA6, CRISPLD2, CFTR2 and CLPTM1L) have been proven to be involved in lung cancer." (PMID 26183581, 2015). "These variants are in linkage disequilibrium (LD) with CLPTM1L and TERT, and both variants are also associated with basal cell carcinoma, lung cancer, glioma and other tumors." (PMID 25007268, 2014). "CLPTM1L is also involved in mitochondrial apoptosis in normal cells, and was reported to be overexpressed in lung cancer cells." (PMID 25007268, 2014). "Recent study also showed that CLPTM1L is overexpressed in lung cancer tissues compared with matched normal lung tissues and its overexpression seems to protect from apoptosis induced by cisplatin." (PMID 25415319, 2014). "rs401681 is located at 5p15.33, a susceptibility region for lung cancer encompassing two known genes TERT (telomerase reverse transcriptase) and CLPTM1L (cleft lip and palate transmembrane protein 1-like)." (PMID 23653681, 2013). "The exact cellular localization of CLPTM1L with respect to its roles in lung cancer progression is currently unclear." (PMID 23300716, 2012). "Common overexpression of CLPTM1L in tumors supports the notion of an oncogenic or tumor promoting role for CLPTM1L in lung cancers." (PMID 22675468, 2012). "To demonstrate the biological activity of CLPTM1L, we examined the effects of decreased CLPTM1L expression on lung cancer cell growth in vitro." (PMID 23300716, 2012). "Here using immunohistochemistry, we found that CLPTM1L expression was markedly increased in lung cancer tissues relative to normal tissues, especially in lung adenocarcinoma." (PMID 23300716, 2012). "Given reports of copy number gain in lung cancer, GWAS evidence, and increased expression of CLPTM1L in cisplatin resistant ovarian tumor cells, we sought to determine if CLPTM1L was overexpressed in lung tumors." (PMID 22675468, 2012). "In particular, an in vitro study provided evidence that CLPTM1L is oncogenic, specifically for Ras-driven lung cancers, in line with its effect on protecting tumor cells from genotoxic apoptosis, and is a promising therapeutic target for therapy-resistant tumors." (PMID 40775447, 2025). "Furthermore, another study revealed that knockdown of CLPTM1L enhances cisplatin-induced apoptosis in lung cancer cells." (PMID 39346724, 2024). "Moreover, 102-5 anti-CLPTM1L treatment also inhibit p-Akt (T308) and 3-D spheroid formation in lung cancer cell lines (A549, NCI-H520, NCI-H226) and in pancreatic cancer cell lines (Panc1, MiaPaca2, and Capan2)." (PMID 33654182, 2021). "CLPTM1L is a mitochondrial protein and is thought to be involved in lung cancer." (PMID 34938740, 2021). "CLPTM1L is dysregulated in many human lung cancer tissues and cells, particularly in NSCLC cells." (PMID 32943060, 2020). "However, a recent study reported that CLPTM1L was a commonly overexpressed anti-apoptotic factor in lung cancer." (PMID 25007268, 2014). "Overexpression of CLPTM1L mRNA has been observed in many cancer types, including lung cancer." (PMID 23738012, 2013). "In addition, over-expression of CLPTM1L has been observed in several types of cancer, including lung cancer." (PMID 24386361, 2013). "Targeting CLPTM1L as well as Bcl-xL may prove to be useful approaches to chemoprevention and lung cancer therapy." (PMID 22675468, 2012). "The specific roles of CLPTM1L in lung cancer cells merit further investigation." (PMID 23300716, 2012).
lung carcinoma (continued). "Here we confirmed that the CLPTM1L protein was more highly expressed in lung cancer, especially in adenocarcinoma, than in normal tissue, This indicated that the practical application of the genetic variations of the gene was not limited to use as genetic markers." (PMID 23300716, 2012). "This indicated that CLPTM1L knockdown could increase chemosensitivity to cisplatin in human lung cancer 95-D cells." (PMID 23300716, 2012). "Here we ascertained whether decreased CLPTM1L expression could increase chemosensitivity to cisplatin in lung cancer cells." (PMID 23300716, 2012). "In addition, we compared relationship between CLPTM1L expression in lung cancer patients with patients’ clinicopathologic characteristics." (PMID 23300716, 2012). "Genetic variants in TERT and CLPTM1L may affect the susceptibility of lung cancer, especially adenocarcinoma in Chinese women nonsmokers." (PMID 23738012, 2013). "In this study, we could not determine the exact biologic changes associated with CLPTM1L overexpression and knock-down in lung cancer cell lines." (PMID 23300716, 2012). "We performed SNP-SNP interaction testing, WTTc, on lung cancer between rs8034191 and SNPs which are typed and untyped on a 1.8Mb region where both TERT and CLPTM1L are located." (PMID 26187382, 2015). "We highlight several isoTWAS associations that demonstrate GWAS colocalization at the isoform level but not at the gene level, including CLPTM1L (lung cancer), LAMC1 (colorectal), and BABAM1 (breast)." (PMID 40775447, 2025). "Additionally, CLPTM1L interacts with PI3K, promoting Ras-induced Akt phosphorylation and contributing to lung cancer development." (PMID 40550808, 2025). "The gene expression results showed that CLPTM1L gene expression is significantly different from adjacent normal tissues in skin and lung cancers." (PMID 39031745, 2024). "We found that CLPTM1L was expressed highly in ovarian cancer, lung cancer and in pancreatic cancer cell lines but not in normal ovarian cell lines, fibroblasts or endothelial cell lines." (PMID 33654182, 2021).
pancreatic cancer (17 papers, 2010 to 2025). "This is consistent with findings from other malignancies, such as lung and pancreatic cancers, where CLPTM1L has been implicated in promoting tumor growth through resistance to apoptosis and activation of the PI3K/Akt pathway." (PMID 40550808, 2025). "Recent research has also demonstrated the tumor-specific expression of CLPTM1L and its involvement in apoptosis resistance, particularly in lung and pancreatic cancers, where it enhances the expression of Bcl-xl, an anti-apoptotic protein." (PMID 40550808, 2025). "Previous studies have also reported the role of CLPTM1L in the proliferation of pancreatic cancer cells and oral squamous cells." (PMID 39346724, 2024). "Research indicates that CLPTM1L fosters tumor proliferation in pancreatic cancer and oral squamous cell carcinoma." (PMID 39346724, 2024). "Additional investigations of anti-CLPTM1L monoclonal antibodies in chemoresistant lung and pancreatic cancers suggest that CLPTM1L is a potential novel target for cancer therapeutics in various cancers." (PMID 33794208, 2021). "Herein we demonstrate re-sensitization of chemotherapy resistant human ovarian tumor cells to carboplatin and pancreatic tumor cells to gemcitabine by human anti-CLPTM1L mAbs as first-in-class biologic drug candidates." (PMID 33654182, 2021). "These SNPs represent independent risk variants at previously identified pancreatic cancer risk loci on chr1q32.1 (NR5A2), chr8q24.21 (MYC) and chr5p15.33 (CLPTM1L-TERT) as per analyses conditioned on previously reported susceptibility variants." (PMID 27579533, 2016). "Little is known about CLPTM1L but recent studies have demonstrated it has an anti-apoptotic role in lung and pancreatic cancer cells." (PMID 25487306, 2015). "One study has linked CLPTM1L expression with cisplatin resistance in an ovarian cancer cell line and more recently, CLPTM1L was shown to promote growth and enhance chromosomal instability in pancreatic cancer cell lines." (PMID 25487306, 2015). "In pancreatic cancer, CLPTM1L functions as a growth-promoting gene and its overexpression might lead to an abrogation of normal cytokinesis and enhance aneuploidy in pancreatic cancer cells." (PMID 36704521, 2022). "In pancreatic cancer, the UPR sensor GRP78 interacts with the extracellular domain of calcium phosphate binding protein 1-like (CLPTM1L)/cisplatin resistance-related protein 9 (CRR9), facilitating the development of chemoresistance." (PMID 41209558, 2025). "In pancreatic cancer models, GRP78-mediated chemotherapy resistance arises from its interaction with the extracellular domain of CLPTM1L/CRR9 on tumor cell surfaces." (PMID 39080273, 2024). "Pattern B, which includes lung, melanoma, and pancreatic cancer, has a broader genome-wide significant signal overlapping both the TERT (chr5: 1,253,282–1,295,178 bp) and CLPTM1L genes (chr5: 1,317,869–1,345,180 bp)." (PMID 34355204, 2021). "The third endometrial cancer risk SNP identified in this study is in the upstream/promoter region of CLPTM1L, ~60 kb away from TERT, and which also harbours several cancer risk alleles, mostly for non-hormone-related malignancies such as lung, bladder and pancreatic cancers." (PMID 25487306, 2015).